TIMP2 (TIMP metallopeptidase inhibitor 2)
Diseases named in the same sentence as TIMP2 in open-access papers (continued):
Sharing a sentence is not in itself a finding about the gene and the disease.
gastric cancer (continued). "Our findings indicated that miR-93 serves as a tumor promoter in human gastric carcinogenesis by targeting TIMP2, suggesting that miR-93 might be a promising biomarker and therapeutic target for treatment of gastric cancer." (PMID 29220395, 2017). "Furthermore, knockdown of TIMP2 with specific siRNA showed similar oncogenic effects in gastric cancer cells with that transfected with miR-93 mimics." (PMID 29220395, 2017). "To figure out the possible mechanisms of how IGFBP3 regulate the invasiveness of gastric cancer cells, we examined the mRNA levels of MMP2/MMP7/MMP9/MMP14, TIMP1/TIMP2, uPA and its receptor uPAR, all of which are invasion-related factors, especially in gastric cancer." (PMID 24386080, 2013). "Therefore, we examined the effect of coronin 3 knockdown or up-regulation on the expression of MMP-9, cathepsin K (based on the results of the PCR array), MMP-2, TIMP-1 and TIMP-2 in gastric cancer after infection." (PMID 22974233, 2012). "Furthermore, we also found the relative expression of TIMP2 was significantly decreased in 70 clinical gastric cancer tissues in which miR-93 was increased, and the expression of miR-93 was negatively correlated with that of TIMP2 in gastric cancer tissues (R2 = 0.33, P< 0.01)." (PMID 29220395, 2017). "Because some gene polymorphisms of MMPs and TIMPs have been found to be related to disease susceptibility and changed gene transcription in vitro, we investigated whether gastric cancer is associated with SNPs of MMP-2, -7, -8 and -9, or their inhibitors TIMP-1 and TIMP-2." (PMID 16940985, 2006). "The potential of andrographolide lies in its ability to impede the progression of gastric cancer by suppressing MMP-2 and MMP-9 activities simultaneously enhancing TIMP-1 and TIMP-2 expression." (PMID 39583105, 2024). "Namely, miR-130b-5p has been shown to promote proliferation and migration in gastric cancer via targeting RASAL1, as well as in osteosarcoma via binding to TIMP2." (PMID 34805186, 2021). "The data suggest a role for chemerin in promoting the invasion of gastric cancer cells via CMKLR1 and GPR1at least partly by reducing TIMP1 and TIMP2 expression." (PMID 30719206, 2019). "Ideally, we should evaluate the gene only after determining the roles of MMPs’ inhibitors, such as TIMP-1, TIMP-2, TIMP-3, and TIMP-4, in the development of gastric cancer." (PMID 29228747, 2017). "Furthermore, the authors suggest that chemerin promotes gastric cancer cell invasion partly by suppressing Tissue Inhibitors of Metalloproteinases TIMP-1 and TIMP-2." (PMID 39590835, 2024). "The diagnostic and prognostic value and potential mechanism of individual TIMPs were illustrated in various cancer types such as TIMP1 in gastric cancer for prediction 6, TIMP1 and TIMP2 in colon cancer for prognosis 7, 8 and TIMP4 in astrocytoma for diagnosis." (PMID 34093812, 2021). "-Analysis Type: Gastric Cancer vs. Normal Analysis-COL8A1; Analysis Type: Gastric Cancer vs. Normal Analysis-FRMD6; Analysis Type: Gastric Cancer vs. Normal Analysis-TIMP2; Analysis Type: Gastric Cancer vs. Normal Analysis-CNRIP1; Analysis Type: Gastric Cancer vs. Normal Analysis-GPR124." (PMID 32095347, 2020). "Notably, KISS1, TIMP2, MMP11, IGFBP1, and EGFR have been reported to be involved in the metastasis of gastric cancer." (PMID 32117443, 2020). "Furthermore, silencing of TIMP2 significantly increased EMT makers including N-cadherin and Vimentin, while decreased E-cadherin expression in gastric cancer cells." (PMID 29220395, 2017). "In the present study, we have provided clear evidence that coronin 3 is highly expressed in metastatic gastric cancer tissues and that coronin 3 can promote gastric cancer metastasis, at least in part by up-regulating cathepsin K and MMP9 expression and down-regulating TIMP2 expression." (PMID 22974233, 2012).
gastric cancer (continued). "The value of MMP-2 as an independent prognostic marker for gastric carcinomas is underscored by our observation that MMP-9, MMP-7, MMP-8, TIMP-1 and TIMP-2 have no prognostic relevance." (PMID 16538217, 2006).
lung carcinoma (31 papers, 2009 to 2026). "In a study population of Taiwanese patients with lung cancer, a high frequency of TIMP-2 loss by LOH and/or promotor hypermethylation in E6-positive lung tumors was found compared with E6-negative lung tumors." (PMID 39409943, 2024). "The effects of a Timp2 functional mutation and administration of recombinant TIMP2 were examined in both orthotopic and heterotopic murine models of lung cancer using C57Bl/6 syngeneic Lewis Lung 2-luciferase 2 cells (LL2-luc2) cells." (PMID 38234759, 2023). "TIMP2-deficient lung cancer cells grown in spheroids exhibit enhanced epidermal growth factor receptor (EGFR) signaling." (PMID 36624735, 2022). "The findings in this study suggested that elevated expression of MMP-2 and TIMP-2 cooperatively correlates with risk of lung cancer." (PMID 29113325, 2017). "We found that the TIMP-2 transcriptional signature in A549 cells is associated with modulation of genes that inhibit endothelial cell proliferation, angiogenesis, lung cancer development and metastasis." (PMID 23371049, 2013). "However, the expression of MMP-2 and its inhibitor the tissue inhibitors of matrix metalloproteinase 2 (TIMP-2) in airways of lung cancer and its diagnostic value is still unclear." (PMID 29113325, 2017). "We have previously reported that TIMP2 expression is a positive prognostic indicator in human breast and lung carcinomas." (PMID 38234759, 2023). "In summary, we describe how TIMP2 exerts novel, anti-tumor effects in a murine model of lung cancer and that rTIMP2 treatment supports a normalizing effect on the tumor microenvironment." (PMID 38234759, 2023). "Within humans, increased levels of MMP2 and TIMP2 were detected in the bronchial alveolar lavage fluid of 48 patients with various types of lung cancers." (PMID 36624735, 2022). "FENDRR suppressed the progression of nonsmall cell lung cancer by regulating the miR-761/TIMP2 (tissue inhibitor of metalloproteinase 2) axis." (PMID 36284300, 2022). "In lung cancer, TIMP-2 has been reported to inhibit tumor growth by promoting an antitumoral transcriptional profile both in vitro and in vivo." (PMID 32984024, 2020). "In conclusion, our study showed that the levels of MMP-2 and TIMP-2 were significantly higher in lung cancer patients than that of benign diseases." (PMID 29113325, 2017). "Recently, numerous studies have demonstrated that MMP-2 and TIMP-2 were involved in lung cancer development and prognosis." (PMID 29113325, 2017). "The level of BALF TIMP-2 was significant higher among patients with lung cancer than patients with benign diseases (4.0 ± 0.4 ng/ml versus 2.8 ± 0.3 ng/ml, P = 0.0371)." (PMID 29113325, 2017). "The results showed a higher level of MMP-2 and TIMP-2 expression and secretion in airways of lung cancer patients than that of benign diseases." (PMID 29113325, 2017). "The percentage of TIMP-2 positive cells in lung cancer patients was significant higher than that of benign group (55.9% ± 5.2% versus 31.0 ± 4.9%, P = 0.0026)." (PMID 29113325, 2017). "We therefore performed the present study to evaluate the expression of MMP-2 and TIMP-2 in airways of lung cancer patients by comparing levels of them in benign diseases." (PMID 29113325, 2017). "A higher expression of TIMP-2 were also observed in airways of lung cancer patients than that of benign group." (PMID 29113325, 2017). "Using a cut-off value of 2.421 ng/ml, the sensitivity, specificity, PPV, and NPV for TIMP-2 in the diagnosis of lung cancer were 62.5%, 57.5%, 63.8%, and 56.1%, respectively." (PMID 29113325, 2017). "MMP-9 was induced in ERK dependent signaling to promote invasion in colorectal cancer, and TIMP2 was noted as a transcriptional signature in inhibiting tumorigenesis and metastasis of lung cancer cells." (PMID 25033461, 2014).
lung carcinoma (continued). "In a similar mechanism to endothelial cells, TIMP-2 was shown to prevent the activation tyrosine kinase-type receptors (TKR) on human A549 (lung carcinoma), MCF7 (mammary adenocarcinoma), HT1080 fibrosarcoma and Hs68 dermal fibroblast cells." (PMID 26056585, 2014). "Previous studies have shown that TIMP-2 enhances the E-cadherin/β-catenin complex in A549 lung cancer cells." (PMID 24519909, 2014). "In conclusion, we show that TIMP-2 promotes an anti-tumoral transcriptional profile in vitro and in vivo, including upregulation of E-cadherin, in A549 lung cancer cells." (PMID 23371049, 2013). "The gene expression level of VEGFA, PGF, and their receptors FLT1 and KDR as well as MMP-2 and the inhibitors TIMP-1 and TIMP-2 was higher in samples from lung cancer resections compared to pneumothorax and transplant biopsy samples." (PMID 22593690, 2012). "Studies in lung cancer cells demonstrated that NF-κB activity was increased by exposure to TIMP-2 as well." (PMID 19627587, 2009). "Similarly, in lung cancer, EV miR-197-3p promotes metastasis by targeting TIMP2/3 in HUVECs, resulting in angiogenesis induction." (PMID 40493409, 2025). "Once MMP-2 is active, it is released, while MMP-14 and TIMP-2 remain attached to the membrane; this event may explain the low levels of MMP-14 and TIMP-2 found in blood from lung cancer patients." (PMID 36213817, 2022). "In this ceRNA network, we found that TIMP2 was a potential target of hsa-miR-200b/c-3p, serving as a natural inhibitor of the matrix metalloproteinases and a potential non-invasive biomarker in kidney cancer and lung cancer." (PMID 34408977, 2021). "Utilizing data from The Cancer Genome Atlas and Genotype-Tissue expression studies, focusing on breast and lung carcinomas, we analyzed the correlation between TIMP2 expression and the transcriptome to identify a list of genes whose expression is highly correlated with TIMP2 in tumor tissues." (PMID 31882975, 2019). "Fourthly, the biological mechanism of how MMP-2 and TIMP-2 modified the risk of lung cancer were not investigated in this study." (PMID 29113325, 2017). "We observed that BALF MMP-2 and TIMP-2 were increased at early stage lung cancer." (PMID 29113325, 2017). "Most importantly, we observed that MMP-2 and TIMP-2 was increased in BALF even at early stage of lung cancer, implying that they might be served as early diagnosis biomarker." (PMID 29113325, 2017). "The present study has demonstrated that MMP-2 and TIMP-2 were useful biomarkers for lung cancer." (PMID 29113325, 2017). "Measurement of MMP-2 and TIMP-2 in BALF might be helpful for differential diagnosis of primary lung cancer." (PMID 29113325, 2017). "Increased TIMP-2 could function by modulating IκBα and IL-8 levels, phosphorylation status of IκBα and NF-κB and thereby directly influence lung cancer progression." (PMID 25888629, 2015). "More specifically, TIMP-2 was determined to decrease the SP in A549 lung cancer cells through decreased transcription of ABCB1 (ATP-binding cassette sub-family G member 1), ABCG2 (ATP-binding cassette sub-family G member 2), and AKR1C1 (Aldo-keto reductase family 1 member C1)." (PMID 26056585, 2014). "Furthermore, the NM demonstrated dose-dependent decrease in MMP secretion and increase in TIMP-2 secretion by both lung cancer A-549 and mesothelioma cell lines." (PMID 23563849, 2013). "More recently, forced expression of TIMP-2 in A549 human lung cancer cells was performed to address whether TIMP-2 overexpression directly influences tumor angiogenesis and/or tumor cell behavior." (PMID 23371049, 2013). "The gene expression level of VEGFA, PGF, and their receptors FLT1 and KDR as well as MMP-2 and the inhibitors TIMP-1 and TIMP-2 was significantly higher in lung cancer specimens compared to pneumothorax samples and biopsies from lung transplant patients (P < 0.001)." (PMID 22593690, 2012).
lung carcinoma (continued). "Therefore, miR-130b may enhance the aggressiveness of lung cancer cells via targeting TIMP-2 or some other molecules in NSCLC cells." (PMID 31061410, 2019). "Gupta further revealed that lung adenocarcinoma cells produce TIMP-1 and TIMP-2, whereas lung SCC cells only express TIMP-2, suggesting that MMP and TIMP differential expression, mediated by the CCR9/CCL25 axis, influences lung cancer metastasis and invasion." (PMID 40607416, 2025). "TIMP2 and KLF2 expression is reduced in lung cancer, and patients with decrease dexpression have a poorer outcome." (PMID 34497265, 2021). "In a recent study, we performed gene expression microarray analysis in lung cancer A549 cells overexpressing TIMP-2 or the mutant Ala + TIMP-2 (devoid of MMP inhibitory activity), to address TIMP-2 mediated transcriptional regulation." (PMID 26056585, 2014). "Despite the high gene expression levels of VEGFA, PGF, FLT1, KDR, MMP-2, TIMP-1, and TIMP-2, only KDR and TIMP-1 were high at the protein level in the lung cancer resections." (PMID 22593690, 2012). "Another study showed that by inducing TIMP-2 expression and decreasing TGF-1, Wogonin inhibited the activity of MMP-2, APN and EGFR-TPK, activated caspase 3, and played an important role in the metastasis and apoptosis of lung cancer A549 cells." (PMID 34630106, 2021). "In another model of TIMP-2 and Ala+TIMP-2 in human lung carcinoma cell line A549, TIMP-2 and Ala+TIMP-2-derived A549 cancer cell lines produced significantly suppressed tumor growth compared to empty vector controls as late as 40 days post tumor cell inoculation." (PMID 29393911, 2018). "As expected, a significant positive correlation was found between the secretion of u-PA and MMP-2 and a significant negative correlation between u-PA and TIMP-2 secretion by NM treatment of lung cancer A-549 cells." (PMID 23563849, 2013). "In this in vitro study, the NM significantly inhibited secretion of u-PA and increased secretion of TIMP-2 in lung cancer cell lines A-549 and Calu-3, as well as decreased MMP-2 secretion in A-549 cells, suggesting its potential in modulating lung cancer invasion and metastasis." (PMID 23563849, 2013). "We analyzed the transcriptional profile of the human lung cancer cell line A549 upon overexpression of TIMP-2 and Ala+TIMP-2 (mutant that does not inhibit MMP activity), and we found changes in gene expression predominantly related to decreased tumor development and metastasis." (PMID 23371049, 2013).
cervical carcinoma (29 papers, 2005 to 2026). A carcinoma arising from either the exocervical squamous epithelium or the endocervical glandular epithelium. "In conclusion, high expression levels of MMP-2 and TIMP-2 in the stroma are significantly associated with poor survival in cervical cancer patients." (PMID 32669083, 2020). "High expression levels of MMP-2 and TIMP-2 in the stroma were significantly associated with poor survival in cervical cancer patients." (PMID 32669083, 2020). "This study aimed to assess whether the expression of MMP-2, MMP-9, MMP-14, TIMP-1, and TIMP-2 in tumors and in the adjacent stroma is associated with cervical cancer prognosis." (PMID 32669083, 2020). "Both over‐ and under‐expression of TIMP‐2 have been reported in different forms of cancer, including lung, breast, gastric, colorectal, and cervical cancers, which indicated quite the opposite prognosis." (PMID 40118773, 2025). "Piperine has been shown to regulate MMP2, MMP9, TIMP1, and TIMP2 in cervical cancer cells at the gene and protein levels." (PMID 36678600, 2023). "Higher concentrations of MMP9 and a lower concentration of TIMP2 were found in patients with cervical cancer and CIN3, compared to patients with ectropion." (PMID 36982551, 2023). "The expression of SerpinE1/PAI-1 and TIMP2 targets also correlated with RECK mRNA levels in cervical cancer samples." (PMID 34066355, 2021). "We found a moderate but significant positive correlation between RECK mRNA and SerpinE1 and TIMP2 mRNA levels in cervical cancer samples." (PMID 34066355, 2021). "In the present study, the ELISA method was used to measure the plasma concentrations of M-CSF, MMP-2, TIMP-2 in cervical cancer patients." (PMID 30820752, 2020). "We investigated the plasma levels and diagnostic power (ROC curve analysis) of M-CSF, MMP-2, TIMP-2 and tumor markers CA 125 and SCC-Ag in cervical cancer (CC) patients as compared to control group." (PMID 30820752, 2020). "In fact, a strong reduction of TIMP2 mRNA was detected in the choriocarcinoma cell line Jar, in the cervical carcinoma cell line HeLa and the invasive trophoblastic cell line HTR." (PMID 31311187, 2019). "This TGF-β1 is then processed by either the epithelial cell specific integrin ανβ6 or by MMPs, especially active MMP-2 in complex with MMP-14 and TIMP-2 on the cell membrane of cervical cancer cells at the epithelial cell–stroma border." (PMID 19352388, 2009). "TIMP-2 is subject to aberrant promoter hypermethylation in human cervical cancer cells and increased methylation favors development of primary cervical cancers." (PMID 15918904, 2005). "TIMP‐2, known as tissue inhibitor of metalloproteinase 2, is differentially expressed in many tumours, including lung, breast, gastric, colorectal and cervical cancers, which also indicates that it may also have different expression levels in tumour patients." (PMID 40118773, 2025). "Additionally, the median value of TIMP-2 (76.00 ng/mL) in the total cervical cancer group was significantly lower compared with the values in healthy subjects (87.25 ng/mL) (p < 0.05)." (PMID 30820752, 2020). "The expression of TIMP-2 could affect in many cancers, such as lung, breast, ovarian, bladder, and cervical cancer." (PMID 31293204, 2019). "Noteworthy, in this previous study, 30 μM cisplatin caused no significant alterations in MMP-9 or TIMP-2 expression in cervical carcinoma cells or in TIMP-2 expression in A549 cells." (PMID 30344920, 2018). "It was reported that the activation of MMP-2 in cervical cancer tissue could be mediated by a functional complex consisting of α(v)β3 integrin/membrane type-1 metalloproteinase-2 (MT1-MMP)/tissue inhibitor of metalloproteinase-2 (TIMP-2) on tumor cell surface." (PMID 30484490, 2018). "A PPIN of 90 genes identified FLT1, IGF2, IRS1, JUN, KDR, ZEB1, TIMP2 (downregulated), and EZH2, SOX2, and MYB (upregulated) in cervical cancer samples when compared with normal samples." (PMID 36879084, 2023).